CD4 (CD4 molecule)
Diseases named in the same sentence as CD4 in open-access papers (continued):
Sharing a sentence is not in itself a finding about the gene and the disease.
infection (continued). "Conclusively, the presented findings show that CD4-positive T-cells are needed to prime protective immunity, but deleting these T-cell subset later, e.g. before challenge infection, does not substantially reduce protection." (PMID 24376753, 2013). "CD4 SP proportion and numbers were not reduced significantly by infection in these C57BL/6 mice (p = 0.14)." (PMID 23554993, 2013). "This difference in post-exposure activity did not correlate with a difference in gene expression during infection or a differential magnitude or quality of the vaccine-specific CD4 T cells induced by ESAT-6 versus TB10.4-containing vaccines." (PMID 24349004, 2013). "In 27 subjects diagnosed with active TB, the median percentage of IFN-γ-secreting CD4+ T-cells was 2.77% versus 0% in 15 negative subjects for active infection." (PMID 24376464, 2013). "In our study, when compared with HIV negative baseline values a significant increase in the level of CCR5 expression on peripheral blood CD4+ T cells from the HIV-1 infected individuals was observed, which is in agreement with the uncontrolled chronic immune activation characterizing this infection." (PMID 23634877, 2013). "The breakthrough infection mouse and the infected vehicle control mice maintained similar peripheral blood CD4+ T cell levels to the HIV-1 negative mice, as we have previously observed with this CCR5-tropic HIV-1 isolate in BLT mice." (PMID 23527295, 2013). "Upon incubation of purified cells or platelets with HIV-1 followed by washing and co-incubation with CD4-positive peripheral blood mononuclear cells (PBMC), platelets, and platelet-RBC complexes, but not platelet-free RBC, caused infection of PBMC." (PMID 24282562, 2013). "Contacts formed between HIV-1 infected and uninfected primary CD4+ T cells induce the transfer of HIV antigens into endocytic compartments in the absence of fusion or infection." (PMID 24244453, 2013). "In addition, a substantial proportion of CD4 T cells produce IL-2 as early as 1 week after lymphocytic choriomeningitis virus (LCMV) and Listeria monocytogenes (Lm) infection and this property is retained as they transition into memory." (PMID 23762323, 2013). "This was accompanied by abundant CD4+ and CD8+ T cells exhibiting an activated phenotype and induction of interleukin 13 (IL-13)- and GATA3-expressing Th2-type CD4+ T cells that remained present in the airways even 14 days after infection." (PMID 23926350, 2013). "Both anti-CSP antibody titres and CSP-specific CD4+ T cells were identified as immunological surrogates of protection, with RTS,S induced anti-CSP antibodies estimated to prevent 32% (95% confidence interval (CI) 24%–41%) of infections." (PMID 23613845, 2013). "Following either systemic or intravaginal infection, almost all PmpG-1-specific CD4 T cells expressed T-bet while no GATA3 expression was detected." (PMID 24204262, 2013). "Mice devoid of the unique receptor for IL-21 (IL21R−/−) have diminished levels of the proinflammatory chemokine KC, and recruit fewer neutrophils, CD4+, CD8+ and gamma-delta T cells to the lungs, and survive longer in response to PVM infection than their PVM-infected wild-type counterparts." (PMID 23342367, 2012). "Consistent with the preferential infection of activated CD4+ T cells by HIV, the infected (HIV p24+) CD4+ T cell population contained a significantly higher proportion of activated T cells than the uninfected (HIV p24-) CD4+ T cell population." (PMID 23029309, 2012). "While in untreated animals all memory CD4+ T-cell subsets (CM, transitional memory [TM] and effector memory [EM]) dramatically declined during the acute phase of infection, none of these subsets was quantitatively reduced in animals receiving IL-7." (PMID 22511868, 2012). "In addition to their role in generating T-dependent B cell responses, CD4+ T cells become IFNγ-producing TH1 cells and cytotoxic effectors that likewise migrate to the lung and aid in resolving the infection." (PMID 22792401, 2012).
infection (continued). "The second assumption is also likely to be overconservative, since D/M virus has been reported to be of lower fitness than R5 virus, so that infection of activated memory CD4+ T cells by D/M virus should not be as efficient as infection by R5 virus." (PMID 22866173, 2012). "Instead, it has been proposed that memory T cells already residing in peripheral tissues at the time of infection—either permanently as in the case of TRM cells, or temporarily as proposed for CD4+ memory T cells—are key to rapid infection control in barrier tissues such as skin and mucosa." (PMID 23162555, 2012). "The CD4-dependent HIVs can infect CD4-negative trophoblastic cells though the infection is 100 times less efficient than CD4-dependent Env-mediated infection." (PMID 23304142, 2012). "Because time of infection is left-censored for the majority of the cohort, survival analyses to determine the impact of clade on time to CD4 decline below a fixed threshold (e.g. 350) were not feasible." (PMID 23185441, 2012). "The impact of the absence of Notch on T cells in the differentiation of CD4+ IFNγ-secreting Th1 cells was assessed six weeks after infection." (PMID 22396647, 2012). "In contrast, the level of Ag85B-specific CD4 T cells did not correlate with protection measured 6 weeks after infection." (PMID 22768165, 2012). "All envelopes were screened for functionality by testing whether env+ pseudovirions conferred infection of HeLa TZM-bl cells, which express recombinant CD4 and CCR5 along with endogenous CXCR4." (PMID 22420378, 2012). "Were also determined the percentage of regulatory T cells CD4+ CD25hi which showed similar levels between infected and uninfected mice, but this population of cells was an apparent decrease in the expression of CTLA4 on the third day of infection." (PMID 22666132, 2012). "In contrast to the expansion of IL-10-producing CD4+ T cells, the frequency of splenic Foxp3+ Treg did not increase during infection, but instead decreased as previously reported." (PMID 22911108, 2012). "The average IL-10 plasma levels of the CD4+ T cell-depleted group increased after infection as in the non-depleted group." (PMID 22533922, 2012). "The expression of the gut-homing molecules integrin β7, CCR6, and CXCR3 was identified as a “signature” for HIV-specific but not CMV-specific CD4+ T-cells thus providing a new explanation for their enhanced permissiveness to infection in vivo." (PMID 22470433, 2012). "Enhanced utilization of CD4 and CCR5 could influence virus transmission since changes in CD4 and CCR5 expression have been shown to impact infection by different HIV-1 strains." (PMID 22693444, 2012). "We chose to focus on visualizing CD4 T cells responding to Salmonella strain BRD509 since this strain has been widely studied previously, and use of more virulent strains precludes analysis at late time points after infection of C57BL/6 mice." (PMID 22275869, 2012). "Using this information in the current study, we demonstrate that the pattern of secretion of IL-2, IFN-γ, and IL-4 by CD4 T cells activated by NC infection is largely independent of epitope specificity and the magnitude of the epitope-specific response." (PMID 22457834, 2012). "In this study, we characterized HIV-1 from a cohort of recently infected individuals in Brazil and attempted to correlate the rate of CD4+ T cell decline with the genetic diversity of infecting HIV strains, including predicted co-receptor use and/or infection by subtype B′′." (PMID 22291931, 2012). "Despite the fact that we observed the same modulation of infection by HIV-1 envelope- and VSV-G-pseudotyped virions, we wanted to investigate whether the TLR stimulation had any effect on CD4 and/or CCR5 expression in MDMs." (PMID 23028330, 2012). "In addition, uninfected BALB/c mice spleens contain slightly higher basal levels of CD4+CD25+FoxP3+ cells, which transiently increased at days 2 and 4 and dropped to the base line by day 8 post-infection." (PMID 22860150, 2012).
infection (continued). "Therefore, 6 days after infection a large part of SupT1 cells were actively killed by the HIV-1 virus, while only a small fraction of primary CD4+ T cells were killed." (PMID 22701517, 2012). "The average IFN-γ plasma levels of the CD4+ T cell-depleted group increased in synchrony with the levels of the non-depleted group up to three weeks post infection." (PMID 22533922, 2012). "Our results show that CD4+ T cells from mice immunized with DnaK+Tul4+GPI responded to DnaK and Tul4 stimulation by producing IFN-γ, IL-10 and IL-17A; and both antigens are processed and presented to CD4+ and CD8+ T cells upon FT LVS infection." (PMID 23209745, 2012). "Since HIV preferentially replicates in activated CD4+ lymphocytes, this relative immune quiescence may decrease the mucosal availability of activated CD4+ T cell targets, making it less likely that sexual HIV exposure will result in productive infection." (PMID 22928014, 2012). "The three major lymphoid-resident cDC subsets, as determined by CD4 and CD8 expression, were all found at the expected frequencies, but individual subsets showed some level of differential regulation of co-stimulatory molecule expression during infection." (PMID 22911108, 2012). "Relative to M. bovis BCG-stimulated CD4+ cells treated with scrambled siRNA, transfection of CD4+ cells with TLR2 siRNA prior to M. bovis BCG stimulation decreased infection with R5 virus from 6.2±0.7% to 3.6±1.0% (p = 0.005), and with X4 virus from 10.7±0.8% to 7.0±1.0% (p = 0.001; data not shown)." (PMID 22844428, 2012). "Along with CD4, HIV-1 typically uses the CCR5 chemokine coreceptor for entry early in infection." (PMID 22319447, 2012). "Using the CD4-VL corrected definition of recent HIV infections, among those patients with confirmed HIV positive serology, 10.22% (95% CI 7.66–13.29) had a recent infection whereas among those with an indeterminate HIV serology, 88.88% (95% CI 51.75–99.71) had a recent infection." (PMID 22363755, 2012). "However, more CD4+ and CD8+ are positive for IFN-γ than γδTCR+ cells in both the lung and spleen at this time point after infection." (PMID 22428026, 2012). "Although treatment with CpG-B alone increased the frequency of CD4+ CD25+ Foxp3+ Treg cells compared to controls, treatment with CpG-B did not alter the frequencies of Treg cells in R. australis-infected WT or IDO−/− mice due to infection itself." (PMID 22470514, 2012). "Since Lm is located in both phagosomes and cytosol of professional antigen-presenting cells during infection, epitopes derived from Listeria proteins are presented by the MHC pathway thereby priming both effector CD4+ and CD8+ T cells resulting in full elimination of Listeria from the host." (PMID 22536395, 2012). "The proportion of human CD4+ and CD8+ T cells among the CD45+/CD3+-gated subsets of PBMCs from HIV-1-infected hNOK/B51Tg and hNOK mice was analyzed every 2 weeks post-infection by using flow cytometry and compared with that among PBMCs from uninfected hNOK/B51Tg and hNOK mice." (PMID 22880104, 2012). "We saw similar results when infection frequencies in CD4+ T cells were used rather than infection frequencies in PBMCs." (PMID 22479485, 2012). "Our data suggest that changes in the levels of miR-31, miR-150, and others in PBMC during infection are the result of regulation and are not entirely (if at all) due to CD4+ T-cell decline." (PMID 22240256, 2012). "It is possible that the main role of DCs in HIV disease is to transmit internalized viral particles to CD4+ T cells rather than to directly support productive infection." (PMID 23344558, 2012). "Our model thus contains an extensive range of latently infected resting CD4+T cells from cells in a pre-integration latent state to cells producing protein without spreading infection." (PMID 22911005, 2012). "As an example, survival times did not correlate with CD4 T cell responses or serum antibody levels during natural infection of resistant mice." (PMID 23093937, 2012).
infection (continued). "The phenotypic profiles of blood T lymphocytes subpopulations show that BT lead to a slight decrease in both CD4+ and CD8+ T cells at day 7th after infection (17% and 21% as compared to 34% and 36% at baseline, respectively) with no changes observed in the MT group (data not shown)." (PMID 22412949, 2012). "This may reflect an increase in the ratio of IFN-γ-secreting to IL-4-secreting CD4 T cells, as we demonstrated in DR1 mice after infection with PR8 compared with NC." (PMID 22457834, 2012). "Regardless of the infective form, the infection with T. cruzi does not alter the percentage of splenic CD4+ T cells." (PMID 22412949, 2012). "After infection with each virus (104 PFU), the thymuses from six mice per group were removed at day 5 p.i., and three thymuses were used for analysis of histopathology and another three for analysis of CD4+CD8+ thymocytes by flow cytometry." (PMID 22719870, 2012). "Additionally, we found that the higher intrathymic TNF-α contents inversely correlated with the thymic relative weight and the relative numbers of CD4+CD8+ cells, thymic parameters that declined along infection." (PMID 22461911, 2012). "This is because HIV-specific CD4+ T-cells express high levels of the HIV coreceptor CCR5 and produce low levels of CCR5 binding chemokines and therefore fail to protect themselves from infection in an autocrine manner." (PMID 22470433, 2012). "Firstly, it seems possible that CD4+ T cells simply don't get a chance to stay in the resting state long enough to maintain a stable integrated pool, since SIV DNA is continuously driven to productive infection because of host cell activation." (PMID 22496643, 2012). "This contrasted with the other cytokines, and even with VL and CD4+ T cell counts, which at this early stage of infection had, respectively, little or no predictive power." (PMID 23056251, 2012). "Lack of CD4+ T cell help has been associated with reduced memory CD8+ T cell development and survival following pathogen infection." (PMID 22792369, 2012). "Splenic CD4+ and CD8+ T cells from mice infected via the i.n. route with FT LVS (7 days post-infection) responded to in vitro stimulation with purified DnaK and Tul4 by producing IFN-γ, demonstrating that DnaK and Tul4 are indeed processed and presented to T cells following infection with FT LVS." (PMID 23209745, 2012). "CD4+ and CD8+ T cells exert different effector functions to control infections." (PMID 22396645, 2012). "HIV/SIV both replicate in macrophages and CD4+ T cells in the oral mucosa, regardless of the route of infection and virus replication seems to activate toll-like receptors (TLR) that are found at high densities throughout the oral cavity." (PMID 23316201, 2012). "We found that agonism of CB2R, but not CB1R, reduced infection in primary CD4+ T cells following cell-free and cell-to-cell transmission of CXCR4-tropic virus." (PMID 22448282, 2012). "In susceptible CC pigs a relative expansion of the CD8+ cell population (reduced ratio of non-specific CD4:CD8 T cells) was observed 3-4 weeks after their primary encounter with the infection." (PMID 22316065, 2012). "It is well established that CD8+ memory cells developed during the primary infection in the absence of CD4+ T cell help are poorly functional although the effector functions of the primary CTL responses are independent of CD4+ T cell help." (PMID 22905277, 2012). "While observations made in this manuscript describe the relationship between HIV-1 and CD4+ T cells, it is in the absence of the multitude of other factors influencing dynamics of infection in vivo." (PMID 22876188, 2012). "They not only inhibit infection of cells by cell-free virus but they can also efficiently prevent virus transmission from virus-infected cells to uninfected CD4+ target T-lymphocytes and DC-SIGN-directed capture of HIV-1 and transmission to CD4+ T lymphocytes." (PMID 22851920, 2012).
infection (continued). "Since the GP33-specific CD8+ T cell response was shown to be T help dependent after VACV-GP-infection, this suggests that lack of CD4 T cell help was not a major reason for poor CD8+ T cell expansion in these mice." (PMID 22916013, 2012). "Previous models have not considered this CD4+ cell response directly but recent research has suggested regulatory T-cells do effect CD4+ cells throughout the infection process." (PMID 22536321, 2012). "We next performed a comparative microarray analysis of mock-infected, uninfected bystander (HSA−) and HIV-1-infected primary human CD4+ T cells (HSA+) in an attempt to identify both virus-induced genes and intracellular environment most permissive to productive infection." (PMID 22876188, 2012). "Presumptive antimicrobial treatment for these infections, including NTS infection, could also be evaluated in clinical trials particularly for patients with very low CD4 counts." (PMID 22761767, 2012). "Altogether, these studies indicate a role of Notch in CD4+ Th1 differentiation, but it is not clear yet which member and how each member of this family contributes to this process during infection with pathogens." (PMID 22396647, 2012). "No significant preference was observed for infection of CD4+ vs CD8+ lymphocytes in individual patient samples (data not shown)." (PMID 22905251, 2012). "As recently shown, the great majority of proliferating and IFN-γ-producing CD4+ cells in the spleen during the early infection are class II MHC-restricted CD4+ T cells and not NKT cells." (PMID 22272258, 2012). "To assess the relevance of Siglec-1 for HIV-1 trans-infection, we pulsed distinct DCs with equal amounts of infectious virus in the presence or absence of blocking reagents and cocultured them with a CD4+ reporter cell line." (PMID 23271952, 2012). "Regarding TNF-α, infection by MT and BT forms triggered different patterns; in the MT group there is a significant increase at days 14, 28 and 42 by CD8+ T cells and on day 28 by CD4+ T cells." (PMID 22412949, 2012). "In contrast to PBMCs, CD4+ T cells do not undergo any significant changes upon infection and thereby, are clearly resistant to H-1 PV despite slight NS1 synthesis." (PMID 22359669, 2012). "In contrast, PDI, but not Trx, was predominantly involved in HIV-1 entry and infection of the CD4+/CCR5+ T cell line, PM-1, and PHA-stimulated primary human T lymphocytes." (PMID 23206338, 2012). "Although T cells have no apparent impact on the outcome of acute lethal PVM infection, both CD4+ and CD8+ T cells are required for virus clearance in response to sublethal infection." (PMID 23342367, 2012). "Other cell populations that increased after infection included macrophages, CD4 and CD8 T cells (data not shown)." (PMID 22496659, 2012). "Moreover, very recent reports have shown that NK cells can have a direct cytotoxic effect towards activated CD4 and CD8 T cells during chronic LCMV Clone 13 infection with an impact on virus-induced immunopathology." (PMID 22876184, 2012). "Our work also demonstrated that DEV vaccines could provoke both specific CD4+ and CD8+ T cell responses to prevent or control infection." (PMID 22770566, 2012). "The induction of the highest specific proliferative response of CD4+ T cells to CD1b+ L-DCs primed with Salmonella was observed 21 days after infection, and no proliferative response was observed for CD4− T cells." (PMID 22279590, 2012). "Suppression of infection, or lack thereof, did not correlate with differential effects on CD4 or CCR5 expression, type I interferon induction, or production of pro-inflammatory cytokines or β-chemokines." (PMID 23028330, 2012). "We were able to narrow the infection of the CD6+ lymphocytes to CD4−CD8+ and CD4+CD8+ T lymphocytes using triple staining for NiV antigen, CD8 marker, and CD4 marker: T cells gated for CD8+ and NiV antigen staining had high percentage of cells with positive staining for CD8+ and NiV." (PMID 22303463, 2012).